AK7 (adenylate kinase 7)
Description:
Nucleoside monophosphate (NMP) kinase that catalyzes the reversible transfer of the terminal phosphate group between nucleoside triphosphates and monophosphates. Has highest activity toward AMP, and weaker activity toward dAMP, CMP and dCMP. Also displays broad nucleoside diphosphate kinase activity. Involved in maintaining ciliary structure and function.
Synonyms: AK 7; FLJ32864; FAP75; CFAP75; SPGF27
Tractability: No criterion of Open Targets' tractability assessment is met for any kind of drug.
Gene: Protein-coding gene on chromosome 14 (96,392,128 to 96,490,031, forward strand). Ensembl gene ENSG00000140057.
Subcellular location: Cytoplasm, cytosol; Cell projection, cilium, flagellum
Subcellular location (Human Protein Atlas): Cytosol; Principal piece
Pathways (Reactome):
Metabolism: Interconversion of nucleotide di- and triphosphates
Gene Ontology:
Molecular function: AMP kinase activity; dCMP kinase activity; nucleoside diphosphate kinase activity; ATP binding; nucleobase-containing compound kinase activity; phosphotransferase activity, phosphate group as acceptor
Cellular component: cytosol; sperm principal piece; motile cilium
Genetic constraint (gnomAD): Loss-of-function variants: 59 observed, 77.59 expected, observed/expected ratio (o/e) 0.76, 90% interval 0.62 to 0.94. The upper end of that interval is the gene's LOEUF score, 0.94, which puts it in group 4 of 6, group 1 being the genes least tolerant of losing a copy. Missense variants: 739 observed, 790.42 expected, observed/expected ratio (o/e) 0.93, 90% interval 0.88 to 0.99. Synonymous variants: 280 observed, 295.26 expected, observed/expected ratio (o/e) 0.95, 90% interval 0.86 to 1.05.
Gene-disease validity (ClinGen):
ClinGen rates the evidence that AK7 causes each of these diseases.
spermatogenic failure (autosomal recessive): Limited. A male infertility characterized by dirsuption of the process of sperm development from diploid cells into mature haploid spermatozoa.
primary ciliary dyskinesia (autosomal recessive): Disputed. A rare, genetically heterogeneous, primarily respiratory disorder characterized by chronic upper and lower respiratory tract disease.
Homologues: Orthologues: chimpanzee AK7 (98% identical), macaque AK7 (97% identical), dog AK7 (88% identical), pig AK7 (86% identical), rat Ak7 (86% identical), mouse Ak7 (86% identical), guinea pig AK7 (82% identical), rabbit AK7 (77% identical), tropical clawed frog ak7 (63% identical), zebrafish ak7b (51% identical), zebrafish ak7a (48% identical), Caenorhabditis elegans F13E6.2 (8% identical), and 1 more. Paralogues in human: AK9 (13% identical), AK8 (11% identical), AK5 (9% identical), AK4 (8% identical), AK4P3 (8% identical), AK2 (8% identical), AK3 (7% identical), AK1 (6% identical), CMPK1 (5% identical).
Diseases named in the same sentence as AK7 in open-access papers:
AK7 is named in the same sentence as 30 diseases in open-access papers, as found by Europe PMC text mining. Sharing a sentence is not in itself a finding about the gene and the disease. The quoted sentences say what the papers report.
primary ciliary dyskinesia (6 papers, 2009 to 2024). "AK7 deficient mice exhibited pathological signs that are characteristic of primary ciliary dyskinesia, such as ultrastructural ciliary defects and reduced frequency of ciliary beating in the respiratory epithelium." (PMID 36982634, 2023). "It has been proven that adenylate kinase (AK) isoforms have an essential role in ciliary function and energy homeostasis, and mutations of AK7 in the mouse result in primary ciliary dyskinesia." (PMID 29890619, 2018). "Recent studies indicate that derangements in adenylate kinase-mediated energetic signaling due to mutations in AK1, AK2 or AK7 isoforms are associated with hemolytic anemia, reticular dysgenesis and ciliary dyskinesia." (PMID 19468337, 2009). "A recent study has demonstrated that a mutation in adenylate kinase 7 (AK7) underlies a primary ciliary dyskinesia phenotype in chronic obstructive pulmonary disease." (PMID 19468337, 2009). "AK7 is a differentiation marker of kinocilia-bearing cells, and mutation in the AK7 gene is associated with human ciliary dyskinesia." (PMID 19468337, 2009). "The presence of the AK7 gene results in a predisposition to ciliary dyskinesia." (PMID 35051222, 2022). "Mutations in the evolutionarily conserved Ak7 gene results in animals presenting with pathological signs characteristic of primary ciliary dyskinesia (PCD), including ultrastructural ciliary defects and decreased ciliary beat frequency in respiratory epithelium." (PMID 19468337, 2009). "Previous studies have indicated that mutations in the AK7 gene could be linked to primary ciliary dyskinesia (PCD) and primary male infertility." (PMID 38970774, 2024). "AK7 is known to maintain ciliary structure and function whose dysfunction may lead to primary ciliary dyskinesia including bronchiectasis and reduced fertility." (PMID 38424222, 2024).
male infertility (5 papers, 2019 to 2025). The inability of the male to effect fertilization of an ovum after a specified period of unprotected intercourse. "In contrast, homozygous AK7 mutations in mice cause ultrastructural defects in motile cilia, male infertility due to decreased sperm production, and severe congenital hydrocephalus leading to death before 8 wk of age." (PMID 38100419, 2023). "Interestingly, in humans, mutation in AK9 also causes male infertility, while mutations in AK7, besides male infertility, were correlated with PCD and caused PCD in mice." (PMID 40886204, 2025). "The majority of previous studies have primarily focused on exploring the role of AK7 in PCD and primary male infertility." (PMID 38970774, 2024).
Infertility (2 papers, 2023 to 2024). "AK7 has been linked to infertility and spermatogenesis failure and may be associated with defects in tail formation, making it a potential molecular marker for the number of healthy litters among reproductive traits." (PMID 39682314, 2024).
ovarian carcinoma (2 papers, 2023 to 2024). A malignant neoplasm originating from the surface ovarian epithelium. "Consequently, only one study to date has examined the prognostic significance of AK7 in ovarian cancer." (PMID 38970774, 2024). "Furthermore, the median overall survival of patients with low AK7-expressing ovarian cancer was shorter than that of patients with high AK7-expressing ovarian cancer, indicating that it may be a prognostic marker for ovarian cancer." (PMID 36982634, 2023).
bile duct carcinoma (1 paper, 2024). "The levels of AK7 expression in bile duct carcinoma, esophageal carcinoma, gastric carcinoma, and endometrial carcinoma were found to be elevated compared to the levels in the respective ordinary tissues." (PMID 38970774, 2024).
Cerebral ischemia (1 paper, 2015). Restriction of arterial blood supply to the brain associated with insufficient oxygenation to support the metabolic requirements of the tissue. "We examined the effects of AK7 in an experimental mouse model of cerebral ischemia." (PMID 25608039, 2015).
colon cancer (1 paper, 2009). "However, Ak7, an α2 function-blocking antibody, was only able to partially abrogate type I collagen-induced effects on colon cancer cell phenotype, suggesting the possible involvement of other collagen receptors." (PMID 19568234, 2009).
Hydrocephalus (1 paper, 2023). Hydrocephalus is an active distension of the ventricular system of the brain resulting from inadequate passage of CSF from its point of production within the cerebral ventricles to its point of absorption into the systemic circulation. "Interestingly, two related adenylate kinases, Ak7 and Ak8, are also highly expressed in sperm and in multiciliated cells, and mutations in the genes that encode these adenylate kinases (AK7 and AK8) cause hydrocephalus." (PMID 38100419, 2023).
kidney cancer (1 paper, 2024). Primary or metastatic malignant neoplasm involving the kidney. "The outcomes confirmed that elevating the levels of AK7 in kidney cancer cell lines via lentivirus, led to a substantial reduction in the growth velocity of mouse tumors." (PMID 38970774, 2024).
lung diseases (1 paper, 2024). "Since PDE4D/AK7 have been previously linked to cAMP/ATP metabolism in lung diseases and now to miR-370-5p in ASMCs, we thus evaluated the effect of high stretch on the cAMP/ATP level inside ASMCs." (PMID 38247802, 2024). "Since PDE4D/AK7 has been previously linked to cAMP/ATP metabolism in lung diseases and now to miR-370-5p in ASMCs, we thus evaluated the effect of high stretch on the cAMP/ATP level inside ASMCs." (PMID 38247802, 2024).
lymph node metastasis (1 paper, 2024). "The expression of AK7 was reduced in individuals with lymph node metastasis compared to those without metastasis." (PMID 38970774, 2024).
renal carcinoma (1 paper, 2024). A carcinoma arising from the epithelium of the renal parenchyma or the renal pelvis. "In addition, following the upregulation of AK7 expression in mouse renal cancer cell line RENCA using lentivirus, we established a subcutaneous tumor model and subsequently administered a combination treatment involving anti-PD1." (PMID 38970774, 2024).
uterine disease (1 paper, 2025). "In cattle, the higher levels of expression of CCDC13, CCDC65, and AK7 genes in healthy cows compared to those with uterine disease is consistent with their expression in subfertile heifers in our study." (PMID 41300775, 2025).
cancer (4 papers, 2021 to 2025). A tumor composed of atypical neoplastic, often pleomorphic cells that invade other tissues. "The findings indicated that the AK7 expression in cancer tissue was notably diminished and it seemed to decrease further with the advancement of ccRCC." (PMID 38970774, 2024). "Our findings revealed great variations in the expression levels of the AK7 gene across different types of cancers." (PMID 38970774, 2024). "Notably, seven UReg genes (GALNT14, KIAA0040, EPB41L1, ZNF469, BLNK, AK7, and WSCD1) are associated with the progression of various cancers in humans." (PMID 40241800, 2025).
neurodegenerative disease (2 papers, 2018 to 2023). A disorder of the central nervous system characterized by gradual and progressive loss of neural tissue and neurologic function. "AK7 has already been tested for its protective role in various neurodegenerative diseases." (PMID 30452468, 2018). "In this sense, even though AK-1 (IC50 = 12.5 μM) is more potent than AK-7 (IC50 = 15.5 μM), it lacks blood–brain barrier (BBB) permeability, a crucial characteristic for the treatment of neurodegenerative diseases." (PMID 38132302, 2023). "Regarding the neuroscience field, where SIRT2 inhibition seems to be an efficient pharmacologic strategy, AK-1, AK-7, and AGK-2 are the most used inhibitors in cellular and in vivo models of neurodegenerative diseases." (PMID 38132302, 2023).
tumor (2 papers, 2021 to 2024). "Our analysis of TCGA data revealed a correlation between diminished AK7 expression and advanced tumor stages." (PMID 38970774, 2024). "Altogether, these results provided further evidence of the tumor-inhibitory properties of AK7 expression." (PMID 38970774, 2024). "Our research indicated that AK7 is notably downregulated in various subtypes of ccRCC, and low AK7 expression is a predictor of unfavorable prognosis among individuals with this type of tumor." (PMID 38970774, 2024). "We initially utilized GTEx and UALCAN to explore the AK7 gene expression in both normal and tumor tissues." (PMID 38970774, 2024). "Based on our cellular experiments, it was observed that downregulating AK7 expression in ccRCC cell line led to substantial enhancement in tumor growth, infiltration, and mobility." (PMID 38970774, 2024). "The findings demonstrated a great deceleration in the tumor growth velocity in mice following AK7 overexpression." (PMID 38970774, 2024). "Furthermore, following AK7 overexpression, the tumor growth velocity of mice in the combined anti-PD1 set exhibited a great deceleration compared to the anti-PD1 set or the group with AK7 over-expression alone." (PMID 38970774, 2024). "Limited research has been conducted on elucidating the involvement of AK7 in tumor development." (PMID 38970774, 2024). "Tumors of AK7, RN5, and ZiP3 grew initially and started to shrink around day 10 after tumor cell inoculation, and completely disappeared around day 20 in IRF3KO mice." (PMID 34768716, 2021).
infection (1 paper, 2018). The state of being infected such as from the introduction of a foreign agent such as serum, vaccine, antigenic substance or organism. "Our study showed diminished translocation of p65 to the nucleus in response to AK7 during infection." (PMID 30452468, 2018). "Post- infection AK7 treatment shows increased IL-2 production during T cell proliferation assay." (PMID 30452468, 2018).
AK7 also shares sentences with these, for which no sentence is quoted: acute lymphoblastic leukemia (1 paper); bronchiectasis (1); chronic obstructive pulmonary disease (1); congenital hydrocephalus (1); endometrial carcinoma (1); esophageal carcinoma (1); gastric carcinoma (1); heart failure (1); Huntington disease (1); leukemia (1); lung adenocarcinoma (1); sarcoma (1); Sepsis (1).